IL37 (interleukin 37)
Diseases named in the same sentence as IL37 in open-access papers (continued):
Sharing a sentence is not in itself a finding about the gene and the disease.
atherosclerosis (continued). "The anti-inflammatory function of IL-37 during atherosclerosis is supported by data from others showing an inverse correlation between IL-37 and M1 macrophage polarisation in human calcified aortic valves, as well as in an animal atherosclerotic model, perhaps via suppressing M1 polarisation." (PMID 34422917, 2021). "These indicated that IL-37 can prevent atherosclerosis by regulating the polarity of macrophages." (PMID 34580597, 2021). "The overexpression of interleukin-37 (IL-37) as antiatherogenic inflammatory cytokine is protected against the inflammatory response by inhibiting proinflammatory cytokines, and IL-37 inhibited atherosclerosis and was a novel cytokine for the prevention and treatment of atherosclerotic diseases." (PMID 33029103, 2020). "It has been reported that IL-37 expression in foam cells, located in the atherosclerotic plaques, has a potential role in the macrophage lipid homeostasis and in the development of atherosclerosis disease." (PMID 33028050, 2020). "These two recent publications indicated that IL-37 could ameliorate atherosclerosis and cardiac remodeling after myocardial infarction in the murine model via targeting DCs." (PMID 31686988, 2019). "From this review, we hypothesize that IL-37 may provide a new therapeutic approach to antagonize or delay the formation of atherosclerosis, to prevent or delay the formation and development of coronary atherosclerotic heart disease or acute coronary syndromes." (PMID 30728750, 2019). "Circulating levels of pro-/anti-inflammatory cytokines, including IL-37, may be related to the pathogenesis of atherosclerosis in patients with either acute coronary syndrome or stable coronary artery disease." (PMID 30728750, 2019). "Predictably, from this perspective, IL-37 may be involved in atherosclerosis-related diseases since it is expressed in the foam-like cells of atherosclerotic coronary and carotid artery plaques." (PMID 30728750, 2019). "Atherosclerosis is perceived to occur as a result of an interplay between elevated lipid content and inflammatory cytokine-driven endothelial dysfunction, several athrogenic features have so far been reported to be ameliorated by IL-37." (PMID 29641433, 2018). "The murine studies that used recombinant IL-37 administration had protective effects on atherosclerosis development and cardiac function in highly inflammatory models, indeed suggesting that systemic IL-37 expression is cardioprotective under conditions of high inflammation." (PMID 28792474, 2017). "Moreover, a recent study showed that recombinant IL-37 treatment reduced atherosclerosis development and improved plaque composition (i.e., reduced macrophage content and increased collagen and smooth muscle cell content) under low inflammatory conditions." (PMID 28792474, 2017). "Moreover, IL-37 is also expressed by human endothelial cells, which play a major role in atherosclerosis progression by functioning as a barrier and mediating the attraction and migration of immune cells into the vessel wall." (PMID 28792474, 2017). "Hence, our present data firstly indicated that IL-37 is involved in innate and adaptive immunity in human atherosclerosis." (PMID 28607385, 2017). "IL-37 has been considered as a protective element in atherosclerosis." (PMID 28039466, 2017). "In addition, we firstly demonstrated that exogenous IL-37 protected mice from atherosclerosis in a diabetic model." (PMID 28607385, 2017).
atherosclerosis (continued). "Our previous study indicated that interleukin (IL)-37 is involved in atherosclerosis." (PMID 28607385, 2017). "Alternatively, it may be possible that other IL-37-expressing cells protect from atherosclerosis development, which would imply that systemic IL-37 expression may be required to prevent the development of cardiovascular diseases." (PMID 28792474, 2017). "Interestingly, Atherosclerosis Signaling was the second highest IPA pathway, and includes genes previously associated with vascular inflammation, such as IL-37, SERPINA1, S100A8, selectin E/SELE, lipoprotein lipase/LPL, and MMP1/3/9." (PMID 26459294, 2015). "However, what role the change in IL-37 levels plays in the development of atherosclerosis and the onset of ACS remains uncertain." (PMID 24733959, 2014). "Notably, emerging evidence highlights interleukin-37 as a protective cytokine with the ability to activate the nuclear factor erythroid 2-related factor 2 pathway, inhibit macrophage ferroptosis, and attenuate atherosclerosis progression in murine models." (PMID 39337246, 2024). "Therefore, the diametrically opposed abundance of IL-37 expression in the arteries representative of these two diseases alludes that the pathophysiological mechanisms involved in atherosclerosis and AAA development may be quite different." (PMID 35602104, 2022). "Moreover, recombinant IL-37 enhances vascular endothelial function by increasing the bioavailability of nitric oxide, and improves systemic insulin sensitivity and glucose tolerance, effects that can potentially prevent atherosclerosis development." (PMID 36613465, 2022). "In addition, it was shown that IL-37 may also attenuate atherosclerosis and atherosclerosis-related diseases through the inhibition of DC activation." (PMID 36613465, 2022). "Finally IL-32 and IL-37 may be protective while IL-34 may contribute to the development of atherosclerosis." (PMID 34422917, 2021). "In recent years, some studies have found that IL-37 might be closely correlated to the growth of atherosclerosis and that IL-37 may inhibit the release of inflammatory factors in atherosclerosis through MAPK inflammatory signaling pathway and inflammatory mediators." (PMID 34580597, 2021). "Similarly, IL-37 has an essential effect on macrophages, reducing the production of various cytokines such as IL-1B, IL-6, and IL-12, cytokines with a critical role in atherosclerosis." (PMID 34199391, 2021). "IL-37 treatment may be a new approach for reducing atherosclerosis." (PMID 33029103, 2020). "In short, the intervention for a variety of factors including IL-37 in the inflammatory response of endothelial cells will provide an innovative way of therapeutic potential and strategy in order to give a more comprehensive and systematic treatment of inflammatory diseases such as atherosclerosis." (PMID 30728750, 2019). "Hence, we hypothesize that IL-37 may protect mice from atherosclerosis via modulating innate and adaptive immunity." (PMID 28607385, 2017). "Therefore, IL‐37 may play a protective role in atherosclerosis through inhibition of inflammatory cytokines production and suppression of macrophage and DC activation." (PMID 28548248, 2017). "Moreover, this study reveals that the protective effect of interleukin-37 against atherosclerosis may involve the inhibition of ROCK activity." (PMID 28039466, 2017). "Therefore, the ELISA and RT-PCR analysis also indicated that IL-37 may ameliorate atherosclerosis through dampening the Th1 and Th17 immune response." (PMID 28607385, 2017). "Therefore, the aim of the present study was to evaluate whether transgenic expression of IL-37 in hematopoietic cells inhibits the accumulation of macrophages in the plaque and is sufficient to protect against atherosclerosis progression." (PMID 28792474, 2017).
atherosclerosis (continued). "Blocking the effects of IL‐18 reduces the atherosclerotic lesion size and induces a switch to a stable plaque phenotype, whereas both endogenous and exogenous IL‐18 accelerated atherosclerosis development 31, 32, suggesting IL‐37 may play a protective role in atherosclerosis via inhibiting IL‐18." (PMID 28548248, 2017). "Finally, we assessed whether the reduced inflammatory state of hematopoietic IL-37 expression would attenuate atherosclerosis development." (PMID 28792474, 2017). "Therefore, IL-37 may attenuate atherosclerosis and atherosclerosis related diseases through the inhibition of DCs activation." (PMID 24733959, 2014). "In one study, overexpression of IL-37 reduced SMA and Vimentin expression in the aorta in atherosclerosis." (PMID 35602104, 2022). "According to the previous studies, IL-37 indeed affects MMP2 and MMP9 expressions in endometriosis, atherosclerosis, and human lung adenocarcinoma." (PMID 32733162, 2020). "Studies have revealed that the concentration of IL-37 increases significantly in the foam or macrophage cells of the atherosclerotic plaque, suggesting that IL-37 released from the atherosclerotic lesion to the blood may play a protective role in the development of atherosclerosis." (PMID 30728750, 2019). "However, whether IL-37 regulates immune response in atherosclerosis remains uncertain." (PMID 28607385, 2017). "Thus, IL-37 could be a promising therapeutic medium to treat atherosclerosis." (PMID 28039466, 2017). "This response of IL-37 to inflammatory processes, such as atherosclerosis, leads to the idea that it functions as a negative feedback mechanism, to diminish the atherogenic effects of excessive inflammation." (PMID 34445530, 2021). "The hypercholesterolemia that was induced in this study was likely the most important driver of atherosclerosis development and, importantly, was not influenced by IL-37 expression." (PMID 28792474, 2017). "In the present study, we show that, under low-grade inflammation, hematopoietic IL-37 expression does not protect from atherosclerosis development." (PMID 28792474, 2017). "Besides liver injury, IL-37 is also involved in cardiovascular diseases, including atherosclerosis, myocardial infarction (MI) and ischemia/reperfusion injury, because IL-37 reduces inflammatory responses in negative feedback mechanisms." (PMID 40264510, 2025). "Notably, IL-37 has been shown to reduce macrophage ferroptosis by upregulating the nuclear factor erythroid 2-related factor 2 (NRF2) pathway, thereby attenuating the progression of atherosclerosis in murine models." (PMID 39337246, 2024). "Two reasons may account for the lack of effect of hematopoietic IL-37 on atherosclerosis development." (PMID 28792474, 2017). "However, hematopoietic IL-37 did not influence hypercholesterolemia and atherosclerosis development." (PMID 28792474, 2017).
inflammatory bowel disease (33 papers, 2012 to 2026). A spectrum of small and large bowel inflammatory diseases of unknown etiology. "For example, a homozygous IL37 loss-of-function mutation has been associated with infantile inflammatory bowel disease, and IL37 genetic variants are linked to impaired trained immunity." (PMID 41087719, 2025). "Given broad immunomodulatory roles, IL-37 has been shown to be directly implicated in several inflammatory diseases, such as systemic lupus erythematosus and inflammatory bowel disease." (PMID 35935954, 2022). "On the contrary, the abundance of circulating IL-37 decreased in patients with inflammatory bowel disease compared to healthy subjects." (PMID 35935954, 2022). "In other inflammatory AIDs, such as inflammatory bowel disease (IBD), the levels of IL-37 are also increased." (PMID 32145751, 2020). "An infant with non-functional IL-37 had suffered from inflammatory bowel disease, proving the importance of IL-37 in the function of mucosal immunity and epidermal barrier." (PMID 35935954, 2022). "Although the mouse ortholog of IL-37 has not been discovered, delivery of the human IL-37 gene to mice showed dampened inflammatory responses in animal models of lipopolysaccharide- (LPS-) induced shock, inflammatory bowel disease, and insulin resistance." (PMID 30918469, 2019).
hepatocellular carcinoma (31 papers, 2012 to 2026). A malignant tumor that arises from hepatocytes. "From a mechanistic standpoint, elevated levels of IL-37 have been associated with increased infiltration of CD1a+ dendritic cells, which notably correlates with the overall survival rate in hepatocellular carcinoma." (PMID 39206201, 2024). "By contrast to gastric cancer, it has been reported that IL-37 suppresses hepatocellular carcinoma (HCC) growth through inhibiting tumor-associated macrophages (TAM), by promoting TAM polarization from the pro-tumorigenic M2 subtype to the anti-tumorigenic M1 subtype." (PMID 39206201, 2024). "IL-37 promotes host anti-tumour immunity by enhancing the recruitment of dendritic cells in hepatocellular carcinoma." (PMID 40191189, 2025). "Evidence from hepatocellular carcinoma indicates that elevated IL-37 levels and the presence of infiltrating CD1a+ dendritic cells are associated with higher overall survival rates." (PMID 40191189, 2025). "It is important to note that several studies have explored the role of IL37 in various other tumours, including renal cell carcinoma, lung cancer, hepatocellular carcinoma, breast cancer, and more." (PMID 39500733, 2024). "In another study of hepatocellular carcinoma, IL-37 converted M2 TAMs into M1 cells by inhibiting the IL-6/STAT3 signaling pathway." (PMID 38033495, 2023). "In the case of human hepatocellular carcinoma (HCC), TAM (tumor-associated macrophage)-derived IL-37 impedes their polarization towards the M2 phenotype by affecting the IL-6/STAT3 axis, eventually inhibiting the growth of the tumor." (PMID 37298214, 2023). "IL-37 has been shown to be protective during the development of a number of cancers, including hepatocellular carcinoma, colorectal cancer, non-small cell lung cancer, renal cell carcinoma and oral and cervical squamous cell carcinoma." (PMID 36483045, 2022). "IL-37 overexpression by TAMs derived from patients with human hepatocellular carcinoma (HCC) inhibits M2 polarization via regulation of the IL-6/STAT3 pathway, to suppress tumor growth in vivo." (PMID 36551790, 2022). "It has been demonstrated that IL-37 inhibits the maturation of M2 macrophages in hepatocellular carcinoma tissues and inhibits angiogenesis." (PMID 36483045, 2022). "The protective role of IL-37 in tumors has been demonstrated in a number of cancers, e.g. in human hepatocellular carcinoma, perhaps via inhibiting M2 macrophages, in lung cancer via inhibiting angiogenesis, and in an animal model." (PMID 35186997, 2022). "This is consistent with the finding that there is a close correlation between the expression of IL-37 on dendritic cells and overall survival of hepatocellular carcinoma cells in vivo." (PMID 36483045, 2022). "As regard the in vivo effect, IL-37 inhibits tumor angiogenesis in the murine orthotopic hepatocellular carcinoma model, suggesting that it can induce an antiangiogenic effect." (PMID 34248996, 2021). "A recent study reported that IL-37 plays an anti-tumor immunity role in the progression of hepatocellular carcinoma through promoting the recruitment of DCs and inducing the activation of DCs." (PMID 34429116, 2021). "Recent studies have reported the antitumor role of IL-37 in various tumor types, such as lung cancer 13,27, colon cancer 28, hepatocellular carcinoma 10,11, renal cancer 29, breast cancer 30, cervical cancer 31 and gallbladder cancer 32 cases." (PMID 32226541, 2020). "Previously, there have been reports suggesting that IL-37 suppresses tumor growth and progression in fibrosarcoma 9, human hepatocellular carcinoma (HCC) 10,11 and lung cancer." (PMID 32226541, 2020). "More recent reports indicate that IL-37 induces autophagy in hepatocellular carcinoma by inhibiting the PI3K/AKT/mTOR pathway and suppresses tumor activity in renal cell and small lung cell carcinoma." (PMID 31781119, 2019).
hepatocellular carcinoma (continued). "Subsequently, it was confirmed in mouse hepatocellular carcinoma model that IL-37 has the effect of inhibiting tumor growth, possibly by increasing the recruitment of CD57+ NK cells to kill cancer cells." (PMID 29805973, 2018). "Recently, it has been demonstrated that IL-37 suppresses tumor progression, including cervical cancer, fibrosarcoma, hepatocellular carcinoma, lung cancer, renal cell carcinoma and breast cancer." (PMID 28467774, 2017). "Recent studies demonstrated that IL-37 has anti-tumor effects in mouse fibrosarcoma, human hepatocellular carcinoma and cervical cancer cells." (PMID 28467774, 2017). "In the mice model, overexpressing IL-37 suppressed fibrosarcoma, non-small cell lung cancer or hepatocellular carcinoma progression." (PMID 28467774, 2017). "Additionally, IL-37 has been found to exert anti-tumor immunity by indirectly promoting dendritic cell recruitment and activation in hepatocellular carcinoma (HCC)." (PMID 40444012, 2025). "Furthermore, a high level of IL-37 has been shown to correlate with increased CD1a+ dendritic cell infiltration, and correlates well with the overall survival rate in hepatocellular carcinoma." (PMID 35186997, 2022). "These include hepatocellular carcinoma, where IL-37 exerted an antiangiogenic role or modulated the phenotype of TAMs by suppressing M2 polarization and regulating proinflammatory cytokine production, and Acute Myeloid Leukemia where IL-37 regulated IL-6 expression." (PMID 35211118, 2022). "Nevertheless, the observation from hepatocellular carcinoma invites speculation that the protective role of IL-37 in breast cancer is perhaps also to boost polarisation of M1 macrophages and subsequently inhibit the growth of breast cancer." (PMID 36483045, 2022). "Higher expression of IL-37 in hepatocellular carcinoma correlates with a better overall survival." (PMID 33746950, 2021). "PBMCs from hepatocellular carcinoma (HCC) patients show M2 polarization and a decreased IL-37 expression." (PMID 34248996, 2021). "Interleukin-37 (IL-37) has recently been recognized as a strong anti-inflammatory cytokine having anti-tumor activity against hepatocellular carcinoma (HCC) in hepatitis B virus (HBV)-infected patients." (PMID 31073186, 2019). "In hepatocellular carcinoma (HCC), patients with high expression of IL-37 in tumor tissue have better overall survival rate and disease-free survival rate." (PMID 29805973, 2018). "In mouse orthotopic models of hepatocellular carcinoma (HCC) and diethylnitrosamine-induced HCC models, IL-37 can inhibit the development of liver cancer by suppressing tumor angiogenesis." (PMID 41293155, 2025). "Furthermore, no mutation within IL-37 gene has been found in all the HCC cases described in The Cancer Genome Atlas - Liver Hepatocellular Carcinoma project (TCGA-LIHC)." (PMID 31073186, 2019). "However, the molecular mechanism of IL-37 in hepatocellular carcinoma (HCC) is largely unclear." (PMID 27835881, 2016). "This protective function of IL-37 in tumours is not exclusive to lung cancer but extends to various other cancers, such as human hepatocellular carcinoma, where it may inhibit the polarization of M1 macrophages and/or angiogenesis in animal models." (PMID 40191189, 2025). "When IL-37 levels are normal, non-hepatocellular carcinoma tissues are minimal and negatively correlated with the tumor size, microvascular metastasis, and BCLC staging of hepatocellular carcinoma." (PMID 33489865, 2020).